CTLA4 (cytotoxic T-lymphocyte associated protein 4)
Diseases named in the same sentence as CTLA4 in open-access papers (continued):
Sharing a sentence is not in itself a finding about the gene and the disease.
gastric cancer (continued). "This indicates that in the gastric cancer microenvironment, Tregs-related molecules (FOXP3) and immune suppressive factors (IL10, TGF-β1), as well as checkpoint molecules (CTLA4), are highly expressed and enriched, jointly shaping an immunosuppressive microenvironment." (PMID 41438510, 2025). "In summary, elevated IL-10 and TGF-β1 levels in gastric cancer synergistically enhance immune checkpoint gene expression, including CD274 and CTLA4, thereby strengthening the immunosuppressive microenvironment and informing immune therapy resistance mechanisms and combined targeted strategies." (PMID 41438510, 2025). "On the basis of these clinical trial results, a combination of PD-1/PD-L1 and CTLA-4 blockade was not indicated for all cases with advanced gastric cancer." (PMID 37048719, 2023). "Furthermore, we found that in both CTLA4- PD1- (P = 0.0002) and CTLA4- PD1+ (P = 0.018) subgroups, cluster 1 gastric cancer patients had a higher immunophenoscore (IPS), indicating better immunotherapy response." (PMID 37711621, 2023). "Anti-CTLA4 immunotherapy has not yet entered the 2022 guidelines for gastric cancer, but the effect of ipilimumab and tremelimumab has been studied in clinical trials." (PMID 36042469, 2022). "In addition, therapeutic strategies targeting other molecules, such as CTLA4, LAG3, Tim3, TIGIT, and OX40, have also been developed to improve the treatment efficacy of gastric cancer immunotherapy." (PMID 36042469, 2022). "In this study, we conducted immunohistochemical studies for PD-L1, PD-1, CTLA-4, and CD8 using tissue microarrays from 464 gastric cancer samples and evaluated the correlations between their expression, clinicopathologic factors, and five-year overall survival." (PMID 27741514, 2016). "Analysis of more than 1000 gastric cancer samples demonstrated that in comparison with Asian tumors, non-Asian gastric cancers had higher expression of T cell markers (CD3, CD45R0, and CD8), including CTLA-4 signaling and lower expression of the immunosuppressive T regulatory cell marker FOXP3." (PMID 35205802, 2022). "In exhausted T cells, these gene markers (PD1, CTLA4, LAG3, TIM3 and GZMB) were consistently significantly correlated with the expression of CLDN10, which further suggested that the expression level of CLDN10 in gastric cancer is related to immune infiltration." (PMID 34721537, 2021). "Interestingly, intratumoral mast cells from gastric cancer constitutively expressed PD-L1 but not other molecules with immunosuppression potential such as CTLA-4 and ICOS." (PMID 31035644, 2019). "Nevertheless, the recent observation that PD-L1 and PD-L2 are expressed in EBV-positive, but not EBV-negative, gastric carcinomas suggests that PD-1/CTLA-4 blockade may be therapeutically useful even for EBV-positive cancers with the less immunogenic forms of viral latency." (PMID 27186886, 2016).
myocarditis (131 papers, 2007 to 2026). Myocarditis is a condition that is characterized by inflammation of the heart muscle (myocardium). "Inhibition of the PD-1/PD-L1 pathway, in particular, has been shown to pose a higher risk for inducing myocarditis compared to CTLA-4 inhibition." (PMID 40255399, 2025). "Cardiac lymphocytic infiltration leading to myocarditis was observed in an animal study wherein mice were deficient of CTLA-4." (PMID 40255399, 2025). "For example, using ipilimumab (anti-CTLA-4 monoclonal antibody) and nivolumab (anti-PD-1 monoclonal antibody) together increases the risk of myocarditis by 4.74 times when compared to using nivolumab just by itself." (PMID 40606990, 2025). "While the link between anti-PD-1 monoclonal antibody therapy and ICI-related myocarditis is well established, the involvement of anti-CTLA-4 monoclonal antibody treatment in causing this condition remains uncertain." (PMID 40606990, 2025). "Nonetheless, preclinical studies offer valuable insights: for example, CTLA-4-deficient mice develop fatal myocarditis early in life, underscoring the essential role of CTLA-4 in maintaining immune tolerance to cardiac tissue." (PMID 40606990, 2025). "Recent studies have also shown that patients receiving PD-1/PD-L1 inhibitors have a higher risk of developing myocarditis (69.1% of cases), compared to those treated with CTLA-4 inhibitors (20%)." (PMID 40255399, 2025). "The role of CD8+ T cells in immune checkpoint inhibitor–associated myocarditis (ICI-MC) has been addressed using a Pdcd1–/–Ctla4+/– mouse model that mimics human ICI-MC." (PMID 39817455, 2025). "A massive upsurge in levels IL-4, colony-stimulating factor and IFN-γ was observed in CTLA-4 deficient mice as against normal mice, which eventually resulted in the induction of lethal myocarditis in animals." (PMID 40255399, 2025). "Different types of ICIs vary in their risk of inducing myocarditis: PD-1 or PD-L1 inhibitors alone can cause myocarditis, but the risk is significantly higher with combination therapy involving PD-1/PD-L1 and CTLA-4 inhibitors." (PMID 41394836, 2025). "Whereas multiorgan lymphocyte infiltration was present in both models, the development of myocarditis was unique to mice born with Ctla4 deficiency." (PMID 39039301, 2025). "We are unable to investigate association between different ICI schemes and myocarditis due to limited number of patients using CTLA-4 (n = 42)." (PMID 40165308, 2025). "For instance, the combined usage of nivolumab (anti-PD-1 mAb) and ipilimumab (anti-CTLA-4 mAb) leads to a 4.74-fold increase in the risk of myocarditis when contrasted with the utilization of nivolumab (anti-PD-1 mAb) as a standalone therapy." (PMID 38375475, 2024). "Given that PD-L1, PD-1, and CTLA-4 play significant roles in the communication between the immune system and the heart, myocarditis has known immune linked etiology." (PMID 38886852, 2024). "Researchers have postulated that T cells play a crucial role in the development of myocarditis associated with ICIs, given the predominant expression of PD-1 and CTLA-4 in T cells." (PMID 38375475, 2024). "In summary, this research not only establishes a reliable mouse model for studying ICIs-associated myocarditis but also highlights the significance of Ctla4 and Pdcd1 in the development of this adverse event." (PMID 38482205, 2024). "Injection of T-cells deficient in Ctla4 triggered a more severe myocarditis compared to animals receiving Ctla4-positive T-cells." (PMID 36979163, 2023). "In terms of drug type, anti-PD-1/PD-L1 and anti-CTLA-4 monotherapy cause irACEs such as myocarditis; anti-PD-1/PD-L1 treatment causes more related pericardial diseases, and more temporal arteritis is caused by anti-CTLA-4 monotherapy." (PMID 37188194, 2023). "Among those receiving combination therapy of CTLA-4 and PD-1 inhibitors, the risk of developing myocarditis is higher than single-agent therapy, and the severity of myocarditis appears to be increased." (PMID 37089888, 2023).
myocarditis (continued). "Animal model studies have shown that cytotoxic T lymphocyte antigen‐4 (CTLA‐4) deficiency can cause myocarditis due to uncontrolled lymphocytic infiltration." (PMID 37180331, 2023). "The CTLA-4-Ig abatacept attenuates ICI-associated myocarditis by blocking T cell stimulation through its ability to bind to B7 ligands." (PMID 37305530, 2023). "One of these is the mouse ICI-myocarditis model consisting of monoallelic loss of Ctla4 and complete deletion of Pdcd1 in C57BL/6 background." (PMID 36139654, 2022). "Loss of CTLA-4 specifically in CD8+ T cells was also studied in a model of CD8+ T-lymphocyte-mediated myocarditis." (PMID 36139654, 2022). "In vivo studies show that CTLA-4 expression in the effector T-cell compartment alone is insufficient for immunosuppression as selective knock-out of CTLA-4 on Tregs causes lymphadenopathy, splenomegaly, myocarditis, and gastritis in mice." (PMID 35326731, 2022). "The combination of anti-PD-1 and anti-CTLA-4 therapy has been identified as one of risk factors associated with ICI-induced myocarditis." (PMID 35844550, 2022). "PD-1 pathway inhibition seems to elicit more cardiotoxicity than CTLA4, and combinational therapy harbors the highest risk of myocarditis." (PMID 35455289, 2022). "Previous research identified combination therapy of anti-PD-1 with anti-CTLA-4 as a risk factor for ICI-induced myocarditis." (PMID 35844550, 2022). "Fatal outcomes saw myocarditis patients treated with an association of ICI (anti-PD-1 + anti-CTLA-4 inhibitors)." (PMID 36142866, 2022). "Based on results from limited clinical studies, myocarditis is more likely to be caused by the CTLA-4 antibody." (PMID 35865949, 2022). "CTLA-4-deficient mice developed lethal myocarditis and pancreatitis with lymphocytic infiltration and tissue destruction and died within 3-4 weeks of age." (PMID 33997442, 2021). "Murine studies have shown that antibodies against CTLA-4 or CTLA-4 deficient murine models both result in the clinical picture of myocarditis." (PMID 34434981, 2021). "As for clinical mechanism, we have learned from murine models that deficiency in CTLA-4 leads to the development of severe myocarditis with T-cell infiltration." (PMID 35047501, 2021). "Very few specific risk factors for ICI-induced myocarditis have been identified to date; combinational therapy consisting of different ICIs (CTLA-4 inhibitor + PD-1 inhibitor) increases the risk of developing ICI-induced myocarditis." (PMID 32405737, 2020). "CTLA-4 deficient mice are known to rapidly develop multi-organ lymphocytic infiltration with severe myocarditis and in another murine myocarditis model CTLA-4−/− cytotoxic T lymphocytes were more pathogenic than CTLA-4+/+ in inducing myocarditis." (PMID 27532025, 2016). "Moreover, data from an international registry identified combination immunotherapy, diabetes mellitus, obesity, and anti-CTLA-4 therapy as independent risk factors for ICI-associated myocarditis." (PMID 40940933, 2025). "Here, we present a case of a patient with gastric adenocarcinoma who developed ICI-induced myositis and myocarditis within 11 days of his first treatment with programmed cell death protein 1 (PD-1) and cytotoxic T-lymphocyte-associated protein 4 (CTLA-4) dual immunotherapy." (PMID 40519473, 2025). "Additionally, in our mouse model for ICI-associated myocarditis, cardiac myosin-specific T cells exhibited an elevated level of CTLA-4 expression compared to bystander T cells." (PMID 38375475, 2024). "Unlike the anti-PD-1 mAb treatment, it is unclear whether the anti-CTLA-4 mAb regimen mediates ICI-associated myocarditis development through the activation of autoreactive T cells targeting cardiac myosin heavy chain." (PMID 38375475, 2024). "Patients treated with pembrolizumab or ipilimumab may also develop fulminant myocarditis with fatal outcomes, however in CTLA-4/PD-1 blocking agents association studies show an increase in myocarditis events compared to monotherapies." (PMID 38322766, 2024).
myocarditis (continued). "Notably, the blockade of the CTLA-4 and PD-1/PD-L1 pathways is significantly associated with the occurrence and progression of both myocarditis and atherosclerosis." (PMID 38375475, 2024). "The paper aims to discuss the incidence of myocarditis related to various types of ICIs, such as antibodies targeting programmed cell death protein-1 (PD-1), programmed cell death Ligand (PD-L1), and cytotoxic T-lymphocyte-associated protein 4 (CTLA-4)." (PMID 38406102, 2024). "The risk of myocarditis may differ between various classes of immune checkpoint inhibitors with anti-CTLA-4 monotherapy (3.3%), anti-PD-L1 (2.4%), and anti-PD-1 agents (0.5%)." (PMID 38672249, 2024). "Animal studies corroborate this, with CTLA-4-deficient mice experiencing spontaneous severe myocarditis and pancreatitis, while PD-1-deficient mice develop lupus-like proliferative arthritis and glomerulonephritis on C57BL/6 background and myocarditis on BALB/c background." (PMID 38375475, 2024). "For example, loss of CTLA-4 or PD-1 in mice induces spontaneous myocarditis." (PMID 38045806, 2023). "At present, it is relatively clear that the risk factors of ICI-induced myocarditis are the concurrent use of ICIs with other cardiotoxic drugs, and the treatment of anti-PD-1/PD-L1 coupled with anti-CTLA-4 may be the strongest risk factor." (PMID 37297017, 2023). "Notably, the coexistence of CTLA-4 and PD-1 disruptions in mice mimics a combined anti-CTLA-4/anti-PD-1 therapy, a risk factor for ICI-associated myocarditis, with CTLA-4-Ig intervention attenuating disease progression." (PMID 38137806, 2023). "Anti-CTLA-4-mediated myocarditis has been associated with giant cell myocarditis." (PMID 36263134, 2022). "T cells in CTLA-4-deficient mice were activated spontaneously and proliferated, and developed lymphoproliferative disorders rapidly, which mediated tissue damage with severe myocarditis." (PMID 36142538, 2022). "Due to the correlation between ICI related arrhythmias and the both two concurrent cardiotoxicities, the low reporting risk of anti-CTLA-4 in myocarditis and pericarditis may lead to low reporting risk of arrhythmias." (PMID 36408225, 2022). "A recent meta-analysis reports a high incidence of myocarditis (about 11 times higher than in other therapies) which reaches a mortality rate of about 50% in case of combination therapies (PD1 / PDL-1 associated to CTLA-4 blocking agents)." (PMID 36158826, 2022). "The development of severe myocarditis was observed in CTLA-4 -deficient mice." (PMID 34660728, 2021). "In turn, the blockage of CTLA-4 was associated with fatal myocarditis." (PMID 34441012, 2021). "CTLA-4 knockout causes severe myocarditis, inflammation of numerous organs, and early death." (PMID 33614750, 2021). "Furthermore, previous studies have highlighted that in terms of susceptibility to myocarditis, anti-PD-1/ anti-PD-L1 are superior to anti-CTLA-4, similar to results obtained in our study." (PMID 33643048, 2021). "Mice deficient in CTLA-4 develop severe myocarditis with massive T cell infiltration." (PMID 30729114, 2019). "Therefore, by activating autoreactive T cells that target cardiac myosin in clinical settings, blocking CTLA-4 with monoclonal antibodies may cause severe myocarditis, much like PD-1 inhibition." (PMID 40606990, 2025). "Thus, CTLA-4 inhibition using mAbs may cause fulminant myocarditis by activating autoreactive T cells targeting cardiac myosin in clinical settings as well as PD-1 inhibition." (PMID 38375475, 2024). "Thus, given the predominantly CD4+ T cell response, the immunoproteasome may play a key role in the development of GCM and myocarditis caused by ICIs directed at CTLA-4." (PMID 34434981, 2021). "In this situation, the patient had steroid-refractory myocarditis and was given abatacept (CTLA4 and PD1/PDL1 pathway inhibitor) along with ruxolitinib (Janus Kinase inhibitor)." (PMID 41141066, 2025).
myocarditis (continued). "The frequency of myocarditis is notably higher with PD-1/PD-L1 pathway inhibition compared to CTLA-4 blockade, with incidence rates of 0.41% and 0.07%, respectively." (PMID 40255399, 2025). "In contrast, ICIs, such as those targeting programmed death-1 (PD-1) and cytotoxic T-lymphocyte-associated protein 4 (CTLA-4), have a well-documented association with myocarditis as a serious immune-related adverse event (irAE)." (PMID 40870916, 2025). "Animal studies have shown that CTLA-4 inhibitors resulted in enhanced myocardial inflammation and eventually myocarditis." (PMID 40255399, 2025). "ICIs, such as those targeting PD-1, PD-L1, and CTLA-4, can lead to irAEs including myocarditis, which is characterized by lymphocytic infiltration and myocardial inflammation." (PMID 40673965, 2025). "As with myocarditis, pericarditis due to anti-PD-1 or anti-PD-L1 monotherapy occurred more frequently compared to anti-CTLA-4 (0.36% and 0.16%, respectively), with an ROR of 2.28 (95% CI: 1.27–4.12)." (PMID 40940933, 2025). "This clearly indicates that PD-1/L1 and CTLA-4 interact together at the genetic level for the manifestation of myocarditis." (PMID 40255399, 2025). "The animals completely devoid of PD-1/L1 and haploid status for CTLA-4 were found to exhibit a high rate (~50%) of mortality due to myocarditis." (PMID 40255399, 2025). "Further, administration of CTLA-4 inhibitors seems to induce higher frequency of cardiovascular complications viz., myocarditis, pericarditis etc.." (PMID 40255399, 2025). "In this study, we explored the involvement of PD-1 and CTLA-4 in cardiovascular complications, particularly atherosclerosis and myocarditis, which can lead to heart failure." (PMID 40255399, 2025). "Clinical evaluation of patients of myocarditis, post-treatment with CTLA-4 and PD-1/PD-L1 inhibitors therapy, showed infiltration of thymocytes in the myocardial and skeletal cells." (PMID 40255399, 2025). "However, it is important to note that these differences may be overestimated and that both anti-PD-1 and anti-PD-L1 agents have a similar toxicity profile.It has been reported that PD-1 and PD-L1 have high levels of expression in heart tissue, and PD-1 and CTLA-4 can cause Myocarditis." (PMID 38979409, 2024). "Adoptively transferring CD8+ T cells from Pdcd1–/– Ctla4+/– mice to Rag1–/– mice led to myocarditis development after two months, emphasizing the pivotal role of CD8+ T cells in fulminant myocarditis." (PMID 39465131, 2024). "The potential therapeutic role of CTLA-4-Ig in mitigating the progression of ICIs-myocarditis is promising and warrants further investigation in clinical settings." (PMID 38482205, 2024). "The incidence of myocarditis varies between different classes of ICIs, with anti-PD-1 agents having the lowest incidence (0.5%) and anti-CTLA-4 monotherapy having the highest (3.3%)." (PMID 38979409, 2024). "Myocarditis has been observed to be more frequently present in combination therapy and with anti-PD-1/anti-CTLA-4 therapy." (PMID 38979409, 2024). "Pharmacovigilance data indicate a low incidence of myocarditis with immune checkpoint inhibitors (ICIs), ranging from 0.27% to 0.9%, with higher rates in combination therapy and anti-PD-1/anti-CTLA-4 therapy." (PMID 39040444, 2024). "Collectively, these findings suggest that blocking CTLA-4 pathways has the potential to contribute to the development of myocarditis and worsen the severity of the disease." (PMID 38375475, 2024). "In 1995, it was found that BALB/c CTLA4−/− mice develop fulminant myocarditis in addition to rapidly lethal lymphoproliferative diseases." (PMID 36672615, 2023). "With regard to myocarditis, in a transgenic Ctla4+/Pdcd1−/− mouse model mimicking ICI-mediated myocarditis, greater mortality and a more severe disease course were observed in female mice." (PMID 37079251, 2023). "The importance of CTLA-4 for the T-cell population during myocarditis was further highlighted in an induced-myocarditis model." (PMID 36979163, 2023).